ENSG00000256825 (novel protein)
Gene: Protein-coding gene on chromosome 12 (133,130,984 to 133,202,369, forward strand). Ensembl gene ENSG00000256825.
Genetic constraint (gnomAD): Loss-of-function variants: 28 observed, 42.26 expected, observed/expected ratio (o/e) 0.66, 90% interval 0.49 to 0.91. Missense variants: 332 observed, 357.83 expected, observed/expected ratio (o/e) 0.93, 90% interval 0.85 to 1.02. Synonymous variants: 142 observed, 130.16 expected, observed/expected ratio (o/e) 1.09, 90% interval 0.95 to 1.25.